MET (MET proto-oncogene, receptor tyrosine kinase)
Diseases named in the same sentence as MET in open-access papers (continued):
Sharing a sentence is not in itself a finding about the gene and the disease.
cancer (continued). "This success suggests that sequencing or switching MET inhibitors may benefit patients with MET-driven cancers who develop resistance to initial therapies." (PMID 39598385, 2024). "ARGX-111 is an afucosylated IgG1 antibody that competitively binds c-MET, inhibits c-MET activity, and downregulates c-MET expression on the cell surface.1234 A clinical phase I trial of ARGX-111 in patients with advanced cancer overexpressing c-MET has been completed (NCT02055066)." (PMID 38763973, 2024). "Notably, MET overexpression contributes to chemotherapy resistance in GBM by promoting the survival of cancer stem-like cells." (PMID 38334610, 2024). "MET transcripts lacking exon 14 can be detected by allele-specific PCR targeted towards the exon 13−15 junction in the cDNA, however, this approach is error-prone because some carcinomas may demonstrate low-abundance MET exon 14 skipping message." (PMID 38966170, 2024). "MET, a proto-oncogene, is transcribed and translated to form c-Met protein, which is a transmembrane tyrosine kinase that takes part in the occurrence and development of a variety of malignant tumours." (PMID 37815881, 2023). "Indeed, preclinical studies investigating the combined inhibition of MET and other pathways have shown significant therapeutic efficacy in various cancer types." (PMID 37887325, 2023). "However, similar to targeting HGF/c-MET, clinical benefits of targeting the Hh pathway are limited to a few cancers such as BCC and MB." (PMID 37919751, 2023). "Notably, 18 of the 74 FECGs enriched in the PI3K-AKT pathway are known cancer driver genes, which include 4 core members of oncogenic MET signaling (HGF, MET, PIK3R1, and PIK3CA)." (PMID 37668356, 2023). "Therefore, targeted therapies against MET constituted appealing strategies for cancer patients carrying MET Exon14 deletion (MET∆14)." (PMID 37760640, 2023). "Its deregulated expression and activation, resulting from MET receptor dimerization and tyrosine autophosphorylation on Y1234/5, have been associated with the onset and progression of several types of cancer and thus led to a great interest in the development of MET-targeting therapeutic compounds." (PMID 37188738, 2023). "In addition, MET supports the stem-like phenotype of cancer cells, affects the expression and activity of stem cell markers, and is associated with chemoresistance." (PMID 37887325, 2023). "In conclusion, our study of clinical HNSCC cohorts showed that dysregulation of the c-MET/STAT3/AKT signaling pathway was linked to the development of HNSCC, as well as its worse prognoses, resistance to treatment, progression of cancer stem cell-like phenotypes, and resistance to certain drugs." (PMID 37373393, 2023). "MET overexpression was found to be oncogenic in OS and essential for the maintenance of the cancer phenotype, and MET inhibitors could inhibit OS growth." (PMID 37546405, 2023). "Although epithelial cells do not typically express HGF, one explanation for this finding could be that HGF transcription is switched on in cancer cells, triggering autocrine MET activation." (PMID 36799689, 2023). "Since the alterations due to non-synonymous mutations in MET gene have a negative effect on human cellular functions and can cause diverse types of cancers in humans, the whole screening of these mutations was required." (PMID 37200850, 2023). "MET activation is involved in angiogenesis, wound healing, cell scattering, proliferation, and cancer invasion and might exert neuroprotective and immunomodulatory effects in the experimental allergic encephalomyelitis model (EAE) of MS." (PMID 38152407, 2023). "Additionally, we will explore the potential of simultaneously targeting the HGF/c-MET axis and Hh pathway as a rational approach for cancer therapy." (PMID 37919751, 2023). "In this context, dual targeting of HER3 or MET seems to be one of the most promising mechanisms, which could overcome the resistance of cancer cells against anti‐HER1 and anti‐HER2 therapy." (PMID 36751113, 2023).
cancer (continued). "MET/HGF-SF signaling could impact the ability of T cells to respond competently to cancer cells, by reducing the DCs’ capacity to present antigens and recruiting immunosuppressive cells." (PMID 37842234, 2023). "As a result, it is believed that MET can be used to identify the functional status of CSCs since it is widely expressed in certain cancers, which could serve as a marker for the proliferation of cells with stem or progenitor cell characteristics." (PMID 38077251, 2023). "In our efforts to uncover the molecular mechanisms underlying the MET-mediated protection from NMDAR2B cleavage, we performed proteomic array screening, simultaneously examining 84 human cancer-related proteins, including proteases and protease inhibitors frequently dysregulated in cancer." (PMID 38201232, 2023). "Capmatinib is an ATP-competitive and highly selective small molecule c-MET receptor TKI that demonstrated inhibition of MET activation in cancer cells whose growth is driven by MET amplification, MET overexpression, MET exon 14 skipping mutations, and HGF-mediated activation." (PMID 38269272, 2023). "Paracrine HGF induces YAP nuclear translocation by binding c-MET, resulting in the crosstalk between CAFs and cancer cells that HGF/c-MET-mediated induces the expression of stemness pluripotency markers such as NANOG, OCT4, and SOX2 in PC cells, as well as increased self-renewal ability." (PMID 37173787, 2023). "Conversely, MSI2 is a crucial regulator of cancer stem cell programs by acting on the stability and translation of target mRNAs that encode key proteins of oncogenic signaling pathways (e.g., TGFβR1/SMAD3, NUMB/Notch, PTEN/mTOR, MET, and MYC)." (PMID 37107676, 2023). "The second explanation could be that GALNT2 initiates O‐glycosylation at the same sites on EGFR and MET, but the glycosyltransferases for further modification of the O‐glycans are differentially expressed in different cancer types." (PMID 36409270, 2023). "MET is known to play a critical role in mediating cross-talk between the MET receptor and Wnt signaling and represents a potential therapeutic target for cancer treatment." (PMID 37829185, 2023). "An early study in hepatocytes revealed that c-MET functionally sequesters the Fas death receptor to prevent apoptosis, suggesting that a high c-MET to Fas ratio may be involved in cancer cell survival." (PMID 37181747, 2023). "Additionally, MET gene amplification leads to the upregulation of cMet, and the subsequent pathway allows cancer cells to bypass EGFR signaling for cell survival, thereby creating another avenue of resistance to our current EGFR-targeted treatments." (PMID 37370772, 2023). "For the large majority of cancer patients, where MET is not mutated, preclinical comprehension of the role of MET can be directly translated to the clinic: MET has anti-apoptotic and pro-invasive functions." (PMID 37760640, 2023). "Moreover, MET has been detected in cancer-related endothelial cells, which are critical for neoangiogenesis." (PMID 37491377, 2023). "MET is a proto-oncogene, receptor tyrosine kinase and its altered expression leads to proliferation, migration, invasion, metastatic spread, and neo-angiogenesis of cancer cells." (PMID 38213901, 2023). "The signaling landscape that accompanies Ephexin3 in various cancer types included the tyrosine kinase receptor MET and the tyrosine phosphatase receptor PTPRF, the serine/threonine kinases MARK2 and PAK6, the Rho GTPases RHOD, RHOF and RAC1, and the cytoskeletal regulator DIAHP1." (PMID 38003617, 2023).
cancer (continued). "Thus, alterations affecting the MET promoter should not be disregarded: re-analyses of TCGA dataset showed a remarkable decrease in promoter methylation in cancer patients, a synonym for transcription activation and MET overexpression." (PMID 37760640, 2023). "The HGF/c-MET signaling pathway is rarely activated in adults except in cancer." (PMID 36789987, 2023). "We also noticed that in cell lines treated singly with either crizotinib or foretinib, the pEGFR/EGFR ratio was elevated, which may indicate that the cancer cells compensate for the reduced pMET/MET ratio by increasing the pEGFR/EGFR ratio." (PMID 37679999, 2023). "Thus, proper paracrine MET activation takes place in the human cancer cells transplanted into these animals, allowing us to fully estimate the contribution of the HGF-MET axis to the cell-autonomous functions involved in the metastatic process." (PMID 37345079, 2023). "Moreover, c-MET is a hepatocyte growth factor (HGF) receptor that has been reported to promote the progression of various cancers." (PMID 35965522, 2022). "It has been reported that LECT2 acts as a potent antagonist of c-MET signaling in many cancer types Thus, we investigated whether exogenous LECT2 affected the c-MET signaling in HCC cells." (PMID 36055405, 2022). "Together, these data support an oncogenic role for a HER3–MPZL3 axis in MET-amplified cancers." (PMID 35249128, 2022). "Notably, this restricted efficacy of systemic c-MET inhibition in cancer is in part related to the inhibition of c-MET in neutrophils." (PMID 35041723, 2022). "Both MET exon 14 skipping mutation (METex14SM) and high copy-number variation (CNV) lead to enhanced carcinogenesis; additionally, programmed-death ligand 1 (PD-L1) is often upregulated in cancers." (PMID 35884507, 2022). "In addition, gene ontology analyses of the clinical GC cohort revealed significant correlation between IFITM3-associated genes and targets of c-MYC, which is a crucial downstream effector of HGF/MET pathway in cancer progression." (PMID 35941699, 2022). "For example, Hgf/MET pathway has become an effective target and biomarker in many cancers." (PMID 36703756, 2022). "The activated MET/HGF pathway promotes EMT in several types of cancers." (PMID 35773658, 2022). "Currently, there is a large body of literature linking the HGF/c-MET pathway to cancer." (PMID 36034555, 2022). "Thus, MET exon 14 skipping mutations and MET amplification act as oncogenic-driven factors and confer EGFR inhibitor resistance to various cancers, including NSCLC, making it a promising therapeutic target." (PMID 36209184, 2022). "MET fusion occurs due to gene rearrangement and has been observed in various types of cancer." (PMID 36483096, 2022). "Thus, these evidences suggest c-MET to be a good target to be used in respect to CAR-T cell therapy in cancer patients." (PMID 35081970, 2022). "GSVA pathway analysis revealed differentially regulated cancer pathways between the three m5C-clusters, including KRAS-related pathways (MAPK-, mTOR-, EGF- and ERK-pathways), cell death pathways (TNFR1-, FAS- and death-pathways), and cancer-related pathways (Wnt-, Gleevec-, MET and CREB-pathways)." (PMID 36060802, 2022). "Therefore, it is expected that CT053PTSA will have exhibit performance in cancer patients with MET, AXL, VEGFR-2 and FLT3 overexpression." (PMID 36341335, 2022). "To test whether HER3 contributed to the oncogenic transformation in MET-amplified cancer cells, we depleted HER3 using two independent shRNA hairpins in MET-amplified EBC1, H1993, and KatoII cells." (PMID 35249128, 2022). "Our data also suggest that in AIPC condition, Menin activates the PI3K/AKT alternative oncogenic pathway and promotes treatment resistance through activation of the oncogene MET, which was reported as a key participant in resistance mechanisms for targeted therapies in multiple types of cancers." (PMID 34711954, 2022).
cancer (continued). "Because MET plays a critical role in cancer progression, its inhibition could have a substantial impact on the treatment outcome of patients with solid tumors with an aberrant MET pathway." (PMID 36483096, 2022). "The HGF/MET pathway is involved in cell motility, angiogenesis, proliferation, and cancer invasion." (PMID 34997350, 2022). "Therefore, when treated with MET inhibitors, it can actually help in cancer progression in patient in such cases." (PMID 35081970, 2022). "It remains to be determined what role MET inhibition plays in toxicity and efficacy and whether dual target inhibition can delay the onset of drug resistance in these cancers." (PMID 34913823, 2022). "Furthermore, transcriptional activation of HGF/c-MET signaling-related genes involved in cancer progression, invasion, metastasis, and cell survival were impaired." (PMID 35778602, 2022). "Dysregulation in HGF/c-MET signaling leading to uncontrolled proliferation, motility, invasiveness, and angiogenesis can play an essential role in the development, progression, and survival of cancer including HNSCC." (PMID 35081970, 2022). "Together, these observations support a role for MPZL3 for proliferation in MET-amplified cells, and that HER3-dependent MPZL3 levels may underlie a requirement for HER3 for robust proliferation in MET-amplified cancers." (PMID 35249128, 2022). "In addition, overexpression of MET is observed in many cancers and is a poor prognostic factor for survival." (PMID 36341335, 2022). "Indeed, in some cases, the HGF/MET axis is crucial for cancer cell survival, and, in other cases, it has anti-cancer effects." (PMID 35986321, 2022). "Indeed, the efficacy of dual NTRK and MET blockade in patients with NTRK fusion-positive cancer that developed MET amplification-driven resistance to a first-generation TRK inhibitor was evaluated in experimental models." (PMID 36556139, 2022). "Since CDCP1 knockdown did not affect MET mRNA expression, it is suggested that CDCP1 functionally interacts with MET and may contribute to the regulation of stability and/or turnover rate of MET protein in these cancer cells." (PMID 35085554, 2022). "This, in turn, can enable combating widespread strategies used by cancer cells to resist the action of drugs, such as MET amplification or PI3K/AKT activation after targeted EGFR inhibition, PI3K/AKT compensation after mTOR inhibition, or MAPK/STAT3 cross-talk." (PMID 35913978, 2022). "In conclusion, we unveil a novel mechanism of MET induction that on the one hand could potentially influence the anti-cancer effects of NOTCH signaling blockade in RMS cells and, on the other hand, could represent a novel vulnerability that can be targeted." (PMID 35574376, 2022). "MET has been identified as a possible therapeutic target in the treatment of cancer." (PMID 36341343, 2022). "Indeed, c-MET was shown to be crucial for the recruitment of anti-tumoral neutrophils, that kill cancer cells following nitric oxide production." (PMID 35041723, 2022). "This is consistent with the recent studies indicating that MET inhibitor could be used more effectively for cancer patients with high MET expression or MET amplification." (PMID 34974522, 2022). "Yet, we cannot exclude the possibility that OVOL1-mediated MET may potentiate the outgrowth of micrometastases at the last step of cancer metastasis in vivo." (PMID 35484112, 2022). "Since then, further research has examined MET signaling pathways in cancers." (PMID 35635086, 2022). "This may further broaden the therapeutic potential of MET inhibition to overcome PARPi resistance in certain cancers." (PMID 35681619, 2022). "As such, inhibition of MET expressed by dendritic cells might contribute to the re-initiation of the activity of T cells, enabling them to kill cancer cells." (PMID 35326642, 2022).
cancer (continued). "Quantitative proteomic analysis of patients’ plasma revealed a possible role for the HGF-MET pathway in LDN-dependent resistance to anti-PD-1 therapy, suggesting the combination of MET inhibitors, known agents in cancer therapy, with anti-PD-1/PD-L1 therapy as an alternative approach." (PMID 36555469, 2022). "All these data along with our results suggest the existence of coregulation between players in triplets such as OIP5-AS1–miR-203a–ZEB2 and OIP5-AS1–miR-203a–c-MET, which is imbalanced by cancer development and may stimulate EMT and metastasis of OC." (PMID 35453574, 2022). "It has been recently shown that transactivation of RON by c-MET may be a feature of cancer cells that are “addicted” to c-MET signaling." (PMID 35069735, 2022). "Moreover, c-Myc alterations contribute to acquired resistance to c-Met inhibitors in different MET-overexpressed cancers." (PMID 35986321, 2022). "We propose that phosphorylated ICAM-1 as an adapter protein may modulate cancer malignancy by further promoting the activity of SRC on the c-MET-SRC axis." (PMID 35487888, 2022). "Including the identified MET amplification, 34.3% of CCA patients harbored mutations and CNAs in oncogenes from the RTK-RAS pathway, and these alterations occurred in a mutually exclusive manner, as reported in other cancers." (PMID 35650238, 2022). "Moreover, activation of MET on dendritic cells in the TME can create a state of immunotolerance for cancer cells by downregulating the inflammatory activity of T-cells through engaging their immune checkpoints." (PMID 35326642, 2022). "Our findings unveil new roles for NMDAR in cancer and suggest that combination therapy with either pathway inhibitor may impair the invasive potential of MET-driven tumors." (PMID 36139568, 2022). "Indeed, the role of aberrant HGF/SF and MET signalling in human cancer has been extensively investigated, and the use of MET agonists in regenerative medicine clearly must meet an adequate safety profile." (PMID 35905995, 2022). "Therefore, the efficacy of MET kinase inhibitors in cancer treatment is reduced by the protumoral effect rising from MET blockage in neutrophils." (PMID 35069735, 2022). "Furthermore, it was also considered that GALNT2 can inhibit cancer development by reducing MET phosphorylation in some conditions, and it was found that cg17737409 site methylation in GLANT2 was helpful for patient's prognosis in this study." (PMID 36060650, 2022). "A clinical study examining samples from 40 patients with RMS found that in the subset of patients whose cancer had infiltrated the bone marrow (n = 16), the infiltrating cells had greater levels of c-MET expression than did cells from the corresponding primary tumors." (PMID 36034555, 2022). "Recurrence of a Met–HER3 crosstalk axis across multiple MET-amplified cancer cell lines further suggests that HER3 may act as a ubiquitous signal transducer downstream from Met in this context." (PMID 35249128, 2022). "Targeting the PAN domain in HGF could act as a multi-pathway target as it entirely shuts down the c-MET signaling cascade and downstream expression of relevant proteins known for their role in cancer prognosis and other diseases." (PMID 35778602, 2022). "Moreover, the MET oncogene that is expressed in many cancer types also results in fibrinolysis inhibition because it has been associated with increased plasminogen activator inhibitor-1 (PAI-1) levels." (PMID 36010924, 2022). "Here, we validated a comprehensive targeted cancer gene panel for simultaneous detection of SNVs and indels in 523 cancer-related genes, CNVs of 69 genes, gene fusions of 55 driver genes including exon skipping events in MET and EGFR, and the immunotherapy predictive markers MSI and TMB." (PMID 35626061, 2022). "Mature HGF retained in the ECM is able to bind its receptor c-MET to mediate cancer progression." (PMID 36324128, 2022).